HOTAIRM1 (HOXA transcript antisense RNA, myeloid-specific 1)
Diseases named in the same sentence as HOTAIRM1 in open-access papers (continued):
Sharing a sentence is not in itself a finding about the gene and the disease.
lung carcinoma (11 papers, 2018 to 2024). "The expression level of HOTAIRM1 in the peripheral blood of lung cancer patients was associated with smoking history (P = 0.039), lymph node metastasis (P = 0.0028), TNM stage (<0.0001), and histological tumor type (P = 0.016)." (PMID 29662483, 2018). "This is exemplified in various cancers: TUG1 in liver cancer; MEG3 and HOTAIRM1 in lung cancer; LINC00355 in bladder cancer; TUC338 in laryngeal squamous cell carcinoma; FTX in oral squamous cell carcinoma; and NNT-AS1 in pancreatic cancer." (PMID 39717771, 2024). "Other authors proved that HOTAIRM1 was conveyed in different types of lung cancer, especially in lung adenocarcinoma, and its transcription activity was considerably diminished in MDSCs from tumor tissues." (PMID 36817434, 2023). "Among the components of the HOTAIRM1/miR-182-5p/ERO1A axis, higher HOTAIRM1 levels exhibit values in predicting worse survival of lung cancer patients." (PMID 36289596, 2022). "The expression of HOTAIRM1 in the PBMCs of patients with lung cancer was lower than that in the PBMCs of healthy controls." (PMID 32083005, 2020). "Conversely, HOTAIRM1 promotes breast cancer, lung cancer, and pancreatic ductal adenocarcinoma by directly regulating HOXA1 expression." (PMID 31477638, 2019). "HOTAIRM1 functions as a tumor suppressor in colorectal, head and neck, gastric, and lung cancers by sponging micro (mi)RNAs and regulating immunosuppressive myeloid-derived suppressor cells." (PMID 31477638, 2019). "On the other hand, HOTAIRM1 levels were shown to be down-regulated in the peripheral blood cells of lung cancer patients compared to those of healthy controls." (PMID 30866866, 2019). "Reduced expression of HOTAIRM1 has been reported in the MDSCs of tumors of patients with lung cancer." (PMID 31404149, 2019). "Correlation between HOTAIRM1 expression and clinicopathological parameters of lung cancer patients (n = 300)." (PMID 29662483, 2018). "By analyzing HOTAIRM1 expression levels in different types of lung cancer, we found that HOTAIRM1 was mainly expressed in lung adenocarcinoma." (PMID 29662483, 2018). "Moreover, the bioinformatics analyses support that the HOTAIRM1/miR-182-5p/ERO1A regulatory axis has significant functions in lung cancer cell proliferation and stemness via regulatory and physical interactions of ERO1A with stemness TFs." (PMID 36289596, 2022). "In this study, the HOTAIRM1/miR-182-5p/ERO1A axis may contribute to lung cancer progression via two collaborators, HOTAIRM1 miR-182-5p and ERO1A." (PMID 36289596, 2022). "Additionally, the expression of HOTAIRM1 and its target gene HOXA1 were negatively associated with the ratio of MDSCs and ARG-1 levels in PBMCs of patients with lung cancer." (PMID 32083005, 2020). "In contrast, Hotairm1 expression is decreased in CD33+ MDSCs from patients with lung cancer." (PMID 33335790, 2020). "In addition, the mechanisms involved in the reduced expression of HOTAIRM1 in lung cancer have yet to be determined." (PMID 31404149, 2019). "Moreover, a positive association has been observed between the expression of HOTAIRM1 and HOXA1 in patients with lung cancer." (PMID 31404149, 2019). "Thus, we isolated CD11b+CD33+HLA-DR−CD14− MDSCs from tumor tissues of lung cancer patients, and qRT-PCR was used to detect the level of HOTAIRM1." (PMID 29662483, 2018). "To confirm the relationship between HOTAIRM1 expression and lung cancer as well as the potential of HOTAIRM1 as a biomarker of lung cancer, we detected the expression level of HOTAIRM1 in the 300 peripheral blood samples collected from patients with lung cancer." (PMID 29662483, 2018). "In the following experiments, we aimed to confirm whether the expression level of HOTAIRM1 in the peripheral blood could be used to reflect the progression of lung cancer." (PMID 29662483, 2018). "Moreover, we found that HOTAIRM1 levels in the peripheral blood of lung cancer patients were significantly decreased compared with those in healthy controls." (PMID 29662483, 2018).
lung carcinoma (continued). "Moreover, the HOXA1 level in the peripheral blood of lung cancer patients was positively correlated with the expression level of HOTAIRM1." (PMID 29662483, 2018). "In addition, the expression level of HOTAIRM1 was significantly decreased in the peripheral blood of lung cancer patients compared with that of healthy controls." (PMID 29662483, 2018). "In addition, the expression level of HOTAIRM1 was increased in the peripheral blood of lung cancer patients postoperation, which was contrary to the expression change of Arg1." (PMID 29662483, 2018). "In addition, HOTAIRM1 levels were observed to be decreased in the peripheral blood cells of lung cancer patients compared with those of healthy controls." (PMID 29662483, 2018). "Moreover, patients with lung cancer have exhibited lower levels of peripheral blood HOTAIRM1 than healthy controls, indicating that HOTAIRM1 might be an ideal biomarker for diagnosing lung cancer." (PMID 34692550, 2021). "Thus, we hypothesize that circulating HOTAIRM1 in the serum of lung cancer patients may be a new marker with which to reflect the progression of lung cancer and the postoperative curative effect." (PMID 29662483, 2018). "Therefore, HOTAIRM1/HOXA1 might be a potential therapeutic target for lung cancer." (PMID 32083005, 2020). "Evidently, MALAT1, HOTAIRM1, and RUNXOR regulate important biological activities (e.g., expansion, differentiation, and immunosuppressive functions) of MDSCs in lung cancer." (PMID 31404149, 2019). "For example, HOTAIRM1 and MALAT1 are down-regulated in MDSCs from lung cancer patients." (PMID 36817434, 2023). "Taken together, this study illustrates that HOTAIRM1/HOXA1 downregulates the immunosuppressive function of MDSCs and may be a potential therapeutic target in lung cancer." (PMID 29662483, 2018). "Similar to HOTAIRM1, HOXA1 expression levels were negatively correlated with the proportion of MDSCs and Arg1 levels and positively correlated with the number of Th1/CTL cells in the peripheral blood of patients with lung cancer." (PMID 29662483, 2018).
acute myeloid leukemia (9 papers, 2015 to 2025). Acute myeloid leukemia (AML) is a group of neoplasms arising from precursor cells committed to the myeloid cell-line differentiation. "A previous study has shown that HOTAIRM1 expression is increased in acute myeloid leukemia, and its expression level is associated with the prognosis of patients." (PMID 37303492, 2022). "A recent clinical study has investigated the clinical impact of HOTAIRM1 and demonstrated that high HOTAIRM1 expression is associated with poor prognosis in intermediate-risk acute myeloid leukemia (AML) patients." (PMID 27146823, 2016). "The lncRNA HOXA Transcript Antisense RNA, Myeloid-Specific 1 (HOTAIRM1) has shown a leading role in the development of acute myeloid leukemia (AML)." (PMID 32723695, 2020). "HOTAIRM1 plays a key role during myeloid maturation and highly expresses in acute myeloid leukemia, which impacts the prognosis of patients." (PMID 30376874, 2018). "Relying on the two PU.1 motifs at the HOTAIRM1 promoter, the increasing expression of PU.1 contributes to the dysregulation of HOTAIRM1 in acute myeloid leukemia cells." (PMID 29905017, 2018). "HOTAIRM1 interferes cytotoxicity in acute myeloid leukemia to alter tumor progression." (PMID 37529170, 2023). "HOX antisense intergenic RNA myeloid 1 (HOTAIRM1) is enciphered in the human HOXA gene cluster and is associated with the maturation of granulocytes and is a key regulator of HOXA genes which are involved in the transcriptional regulation of acute myeloid leukemia (AML) and normal hematopoiesis." (PMID 28465674, 2017).
breast carcinoma (9 papers, 2014 to 2025). "Taken together, these data suggest that HOTAIRM1 is associated with tamoxifen resistance in ER+ breast cancer cells." (PMID 32284737, 2020). "On the other hand, Hotairm1 is a long non-coding RNA that has been reported to promote tamoxifen resistance in breast cancer by enhancing HOXA1 upregulation." (PMID 38802425, 2024). "Studies done previously from the western population have shown HOTAIR lncRNA to be overexpressed in HER2+ breast cancers and HOTAIRM1 in basal-like breast cancers." (PMID 36386805, 2022). "First, we examined the expression level of HOTAIRM1 between ER+ breast cancer cells (MCF7 and T47D) and tamoxifen-resistant breast cancer cells (TAMR) by RT-qPCR." (PMID 32284737, 2020). "Here, we propose that HOTAIRM1, a highly expressed lncRNA in tamoxifen-resistant breast cancer cells, is a novel marker for tamoxifen resistance." (PMID 32284737, 2020). "Our study reveals for the first time that HOTAIRM1 is not only involved in cancer progression, but is also a marker of tamoxifen resistance in breast cancer." (PMID 32284737, 2020). "In the present study, we showed that the lncRNA HOTAIRM1 is upregulated in tamoxifen-resistant breast cancer cells (TAMR), compared to levels in ER+ breast cancer cells (MCF7)." (PMID 32284737, 2020). "Our study focused on the mechanism by which HOTAIRM1 regulates HOXA1 in tamoxifen-resistant breast cancer cells." (PMID 32284737, 2020). "For example, HOTAIR is a lncRNA that is highly expressed in HER2+ breast cancers whereas HOTAIRM1 is highly expressed in basal‐like subgroup of breast cancers." (PMID 30959550, 2019). "For example, we found that the HOTAIRM1 was overexpressed in the basal-like subtype of breast cancer." (PMID 25296969, 2014). "To examine whether HOTAIRM1 functions as a regulator of the adjacent HOXA1 gene transcription in tamoxifen-resistant breast cancer cells, we treated TAMR cells with siHOTAIRM1 and examined the expression of anterior HOXA genes." (PMID 32284737, 2020). "Together, our findings suggest that HOXA1 and its neighboring lncRNA, HOTAIRM1, might serve as potential therapeutic targets for ER+ breast cancer patients who have acquired tamoxifen resistance." (PMID 32284737, 2020). "Further exploration of the molecular mechanisms of the HOTAIRM1/HOXA1 axis may provide more insight in the pathogenesis of breast cancer." (PMID 32284737, 2020). "In addition, this gene expression pattern was also observed in breast cancer tissues through HOTAIRM1-mRNA correlation analysis using TCGA data retrieved from TANRIC." (PMID 32284737, 2020). "Knockdown of HOTAIRM1 or HOXA1 could re-sensitize TAMR cells to tamoxifen treatment, suggesting that the HOTAIRM1/HOXA1 axis contributes to tamoxifen resistance in breast cancer." (PMID 32284737, 2020). "Only high expression of LINC01128, CCDC18-AS1, SH3BP5-AS1, HOTAIRM1, LINC01140, SGMS1-AS1, LINC01578 or LINC00667 had favorable prognosis in breast cancer." (PMID 34828282, 2021). "Conversely, breast cancer (BRCA), colon adenocarcinoma (COAD), kidney chromophobe (KICH), and rectum adenocarcinoma (READ) were found to be characterized by lower HOTAIRM1 expression levels (p < 0.05)." (PMID 34805277, 2021). "The lncRNA HOTAIRM1, known to be involved in myelopoiesis as well as transcriptional regulation of the HOXA genes in embryonic stem cells, is also expressed in breast cancer cells." (PMID 32284737, 2020). "Our results revealed a novel mechanism which demonstrates that HOTAIRM1 and HOXA1 could be promising therapeutic targets for patients with ER+ breast cancer who have acquired tamoxifen resistance." (PMID 32284737, 2020). "To further validate the clinical relevance of HOTAIRM1 and HOXA1, we analyzed a publicly available clinical in silico dataset comparing 60 paired primary ER+ breast cancer patients to recurred cancer patients following tamoxifen mono-therapy for 5 years (GSE1379)." (PMID 32284737, 2020).
breast carcinoma (continued). "Nevertheless, no study has been conducted to investigate the role of HOTAIRM1 in drug resistance in breast cancer." (PMID 32284737, 2020). "Those lncRNAs include some already known to be involved in cancer, such as H19 and HOTAIR, as well as novel lncRNAs never reported in breast cancer (e.g., HOTAIRM1)." (PMID 25296969, 2014). "However, the regulatory role of HOTAIRM1 on HOXA1 transcription in breast cancer, more specifically tamoxifen-resistant breast cancer, remains unknown." (PMID 32284737, 2020).
hepatocellular carcinoma (8 papers, 2019 to 2025). A malignant tumor that arises from hepatocytes. "Based on a literature analysis, we identified MEG3 and HOTAIRM1 as inhibitors of the Wnt/β-catenin pathway in oral squamous cell carcinoma, melanoma, and hepatocellular carcinoma, suggesting a broader tumor-suppressive role." (PMID 40350996, 2025). "For example, in hepatocellular carcinoma and gastric cancer, HOTAIRM1 prevents cancer progression by suppressing signaling cascades such as the Wnt and the PI3K/AKT pathways 32,33." (PMID 32284737, 2020). "However, a study reported that an alternatively spliced variant of RIZ1 (RIZ1v2) is upregulated in hepatocellular carcinoma (HCC) cells, promoting tumor progression through an HOTAIRM1/miR-125b axis." (PMID 40867614, 2025). "Recent data show that HOTAIRM1 is a lncRNA that is abnormally active in different tumours and is related to hepatocellular carcinoma, colorectal, gastric, head and neck, ovarian, thyroid cancers, etc.Some authors detected that HOTAIRM1 expression was significantly reduced in tumour tissues." (PMID 36817434, 2023).
non-small cell lung carcinoma (6 papers, 2021 to 2023). A group of at least three distinct histological types of lung cancer, including non-small cell squamous cell carcinoma, adenocarcinoma, and large cell carcinoma. "In Addition, Feng Xiong and colleagues studied expression levels of HOTAIRM1 on different tumor cell lines of non-small cell lung cancer." (PMID 37047453, 2023). "HOTAIRM1 silencing inhibits cell glycolysis metabolism and tumor progression in non-small cell lung cancer." (PMID 36289596, 2022). "Rescue experiments were carried out to confirm the role of HOTAIRM1/miR-328-5p/SPON2 pathway in promoting the migration and invasion of non-small cell lung cancer." (PMID 36153414, 2022).
gastric cancer (5 papers, 2019 to 2025). A primary or metastatic malignant neoplasm involving the stomach. "HOTAIRM1 suppresses the PI3K/Akt pathway in gastric cancer by sponging miR-17-5p, leading to increased PTEN expression." (PMID 40350996, 2025).
lung adenocarcinoma (5 papers, 2018 to 2023). A carcinoma that arises from the lung and is characterized by the presence of malignant glandular epithelial cells. "In our study, we found that HOTAIRM1 in lung adenocarcinoma cell exosomes, as upstream of miR-328-5p, can reduce their anti-tumor effects through competitive adsorption of the miRNA." (PMID 36153414, 2022). "It has been reported that the expression of HOTAIRM1 is evidently downregulated in lung adenocarcinoma tissues, and the growth of H1650 and PC-9 cell lines were accelerated by promoting cell-cycle progression when HOTAIRM1 was silenced." (PMID 35087800, 2021). "Definitive therapy targeting on SPON2 or HOTAIRM1 in tumor microenvironment may improve the therapeutic effect of lung adenocarcinoma." (PMID 36153414, 2022). "Secondly, this study found that SPON2 can be derived from the exosome HOTAIRM1 of lung adenocarcinoma cells, which can affect the expression by competitive adsorption of miR-328-5p, so as to promote the invasion and metastasis of lung adenocarcinoma." (PMID 36153414, 2022).
ovarian carcinoma (4 papers, 2020 to 2022). A malignant neoplasm originating from the surface ovarian epithelium. "In ovarian cancer, silencing HOTAIRM1 promoted cell proliferation and inhibited cell apoptosis by regulating the Wnt pathway and its downstream target gene MMP9." (PMID 35087800, 2021). "And miR-106a-5p promoted ovarian cancer progression by targeting ARHGAP24, while lncRNA HOTAIRM1 sponged miR-106a-5p and inhibited ovarian cancer development." (PMID 33290256, 2020).
thyroid cancer (4 papers, 2020 to 2023). "HOTAIRM1 (HOXA Transcript Antisense RNA Myeloid-Specific 1) is upregulated in patients with thyroid cancer and positively correlates with patient TNM stage and lymph node metastasis." (PMID 36814601, 2023). "Overall, HOTAIRM1 inhibits miR-148a, which allows for aberrant expression of WNT10B in thyroid cancer." (PMID 36814601, 2023). "shRNA (small hairpin RNAs) knockdown of HOTAIRM1 markedly increased expression of miR-148a and decreased expression of WNT10B in thyroid cancer cell lines (TPC-1 and BCPAP)." (PMID 36814601, 2023). "The results of this study revealed that the lncRNAs HOTAIRM1 and PCA3 are upregulated during thyroid cancer development and progression." (PMID 32760219, 2020).
myeloid leukemia (3 papers, 2015 to 2022). A clonal proliferation of myeloid cells and their precursors in the bone marrow, peripheral blood, and spleen. "For instance, the autophagy-related lncRNA HOTAIRM1 is implicated in the regulation of autophagy levels in myeloid cells and drives the development of myeloid leukemia." (PMID 35706412, 2022). "In addition, our findings were supported by those of a previous study indicating that HOTAIRM1 expression was elevated in myeloid leukemia cells." (PMID 34615546, 2021).
pancreatic ductal adenocarcinoma (3 papers, 2019 to 2024). An infiltrating adenocarcinoma that arises from the epithelial cells of the pancreas. "On the other hand, high expression of HOTAIRM1 has been associated with oncogenicity in pancreatic ductal carcinoma by promoting proliferative and migratory abilities." (PMID 32284737, 2020). "However, HOTAIRM1 was also shown to promote cell proliferation and migration in pancreatic ductal adenocarcinoma." (PMID 31477638, 2019).
allergic rhinitis (2 papers, 2023). Inflammation of the nasal mucous membranes caused by an IgE-mediated response to external allergens. "Besides, HOTAIRM1 was highly expressed in allergic rhinitis, thereby exaggerating the adverse reactions triggered by allergen." (PMID 37529170, 2023).